OPA1 (OPA1 mitochondrial dynamin like GTPase)
Diseases named in the same sentence as OPA1 in open-access papers (continued):
Sharing a sentence is not in itself a finding about the gene and the disease.
hearing loss (15 papers, 2010 to 2026). "The pivotal role of OPA1‐mediated excessive mitochondrial fission plays in the occurrence and development of age‐related hearing loss." (PMID 38267829, 2024). "Although most studies broadly qualify the hearing disorder as ‘sensorineural hearing loss,’ some authors have proposed that auditory neuropathy is the pathophysiologic mechanism underlying the hearing impairment in OPA1-ADOA." (PMID 39442262, 2024). "Mutations in OPA1, currently recognized as the sole fusion protein GTPase located in the inner mitochondrial membrane, can lead to syndromic hearing loss." (PMID 38267829, 2024). "However, there have been no studies reporting on the connection between acetylation modifications of OPA1 and cochlear disorders, including hearing loss." (PMID 38267829, 2024). "OPA1 functions as both a necessary gene regulating mitochondrial fusion and a pathogenic gene responsible for auditory neuropathy, suggesting that an imbalance in mitochondrial dynamics may play a critical role in hearing loss, but relevant studies are few." (PMID 36278017, 2022). "Hearing impairment, which affected nearly 15% of the reported families, was mainly observed in Wolfram syndrome and autosomal dominant hearing impairment caused by WFS1 variants, followed by variants of POLG, OPA1, DNMT1 and SLC25A46." (PMID 39423307, 2025). "Potential causative variants were identified in genes associated with nonsyndromic hearing loss (CIB2, COL11A1, ILDR1, MYO15A, TMPRSS3, and WFS1), nonsyndromic hearing loss or Usher syndrome (CDH23, MYO7A, PCDH15, and USH2A), and other syndromic forms of hearing loss (CHD7, OPA1, and SPTLC1)." (PMID 34837038, 2022).
hereditary optic neuropathy (15 papers, 2010 to 2024). "In this study, we analysed mitochondrial distribution and ultrastructure in the retina and longitudinal optic nerve sections of pre-symptomatic hereditary optic neuropathies mouse models with Opa1 and Nd6 deficiency to identify early mitochondrial changes." (PMID 39659974, 2024). "ADOA is the most common form of hereditary optic neuropathy, with a reported frequency of 1:10,000, and is caused by heterozygous variants in the OPA1 gene encoding a mitochondrial dynamin-related large GTPase." (PMID 39442262, 2024). "Lastly, the keyword variants reflect increased research on genetic mutations, particularly in OPA1, which is pivotal in hereditary optic neuropathies." (PMID 39835089, 2024). "Dominant optic atrophy (DOA) is the most prevalent form of hereditary optic neuropathy with a frequency of 1:20 000, and is caused mainly by heterozygous variants in OPA1, encoding an ubiquitous mitochondrial dynamin large GTPase." (PMID 38334784, 2024). "This study expanded the OPA1 mutation spectrum, and our results showed that OPA1 mutation is another common cause of childhood-onset hereditary optic neuropathy in Chinese pediatric patients, especially those with disease onset during preschool age." (PMID 28081242, 2017). "The purpose of this study was to detect OPA1 gene mutations and associated phenotypes in Chinese patients with suspected hereditary optic neuropathy." (PMID 23401657, 2013). "In this study, Sanger sequencing was used to detect the mutation of OPA1 in 193 Chinese families with suspected hereditary optic neuropathy, in which the three common LHON-associated primary mutations of mtDNA had been excluded with prior screening." (PMID 23401657, 2013). "Recently, analysis of OPA1 in some large case series of hereditary optic neuropathy in Caucasians suggested that scanning the most frequently mutated exons might be a good strategy for identifying OPA1 mutations." (PMID 23401657, 2013). "Indeed, mutations in OPA1, a profusion protein that causes hereditary optic neuropathies and mutations in MFNs and other fusion molecules, affect the function of placental cells, skeletal muscle cells, vascular smooth muscle cells, and peripheral motor neurons." (PMID 28409163, 2017). "The mutation rate (38.3%) of OPA1 mutations in this EON cohort was higher than that (9.6 and 7.6%) reported in a group of Chinese patients with suspected hereditary optic neuropathy and other Han Chinese population." (PMID 34676220, 2021). "The present study was designed to survey the mutation spectrum of common pathogenic genes (OPA1, OPA3 and mtDNA genes) and to analyze the genotype-phenotype characteristics of Chinese patients with suspected childhood-onset hereditary optic neuropathy." (PMID 28081242, 2017). "Optic atrophy type 1 (OPA1), a hereditary optic neuropathy, is one example of a chronic neurodegenerative disease caused by mutations in the OPA1 gene that encodes a mitochondrial dynamin-related GTPase that functions in maintenance of mitochondrial morphology, including fusion, and metabolism." (PMID 21258649, 2010). "Unexpectedly, we observed that 73% (19/26) of patients with OPA1 mutations in the DOA group were initially misdiagnosed with LHON before genetic analysis, which indicated that DOA is not widely recognized as a major cause of hereditary optic neuropathy by ophthalmologists in China." (PMID 28081242, 2017).
Behr syndrome (14 papers, 2012 to 2025). A disorder characterized by early-onset optic atrophy along with neurological features, including ataxia, spasticity, and intellectual disability. "Optic atrophy type 1 and ADOA-plus syndrome are caused by mutations in the OPA1 gene in one copy of the gene in each cell, but Behr’s syndrome is caused by mutations in both copies of the OPA1 gene in each cell." (PMID 36980899, 2023). "Early-onset visual impairment with Behr syndrome phenotype should be considered suspicious for biallelic OPA1 variants." (PMID 35741767, 2022). "Our case is the first reporting a novel missense OPA1 variant co-occurring with a chromosomal microdeletion leading to a severe phenotype reminiscent of Behr syndrome." (PMID 32883255, 2020). "Biallelic pathogenic variants in the OPA1 gene are associated with Behr syndrome (MIM# 210000)." (PMID 33578638, 2021). "We report here three patients with biallelic OPA1 mutations: a boy showing an early-onset and severely progressive mitochondrial disorder and two girls showing a spastic ataxic syndrome associated with sensory motor peripheral neuropathy, resembling Behr syndrome." (PMID 28494813, 2017). "Behr’s syndrome (OMIM #210000), the most severe condition caused by OPA1 gene mutations, is accompanied by neurological issues that start in early life." (PMID 36980899, 2023). "Mutations in both copies of the gene significantly limit the quantity of effective OPA1 protein, which most likely contributes to the severe Behr’s syndrome symptoms and manifestations." (PMID 36980899, 2023). "While this report does not provide a new genetic finding, it reminds us how rare Behr syndrome with biallelic pathogenic variants in OPA1 is." (PMID 35741767, 2022). "A literature review of reported biallelic OPA1-related Behr syndrome was performed." (PMID 35741767, 2022). "Particularly patients with severe course of disease revealed no changes in mtDNA, for example one patient carrying an OPA1 mutation and diagnosed with Behr syndrome, as well as the two children that carry compound heterozygous OPA1 mutations." (PMID 24067127, 2013). "Autosomal recessive OPA3 mutations have been identified in Iraqi Jewish patients presenting with Behr syndrome and 3-methylglutaconic aciduria (Costeff syndrome) and more recently autosomal dominant and recessive OPA1 mutations were shown in Behr syndrome without metabolic abnormalities." (PMID 32656641, 2020).
sarcopenia (14 papers, 2018 to 2025). Progressive decline in muscle mass due to aging which results in decreased functional capacity of muscles. "The Opa1–/– mouse model is a well-known model that recapitulates key pathophysiological aspects of sarcopenia-related muscle loss and strength." (PMID 37551712, 2023). "Other studies have shown that the progression of sarcopenia involves impaired mitochondrial quality, which is marked by the reduction or loss of OPA1, MFN2, and DRP1 expression." (PMID 35432979, 2022). "Indeed, acute inhibition of OPA1 in adult animals led to a geriatric phenotype with the classical features of sarcopenia such as muscle mass and strength loss, denervation, and exercise intolerance in just 3 months." (PMID 37551712, 2023). "Interestingly, both fusion and fission machinery are suppressed in aging sarcopenia, cachexia, and chemotherapy-induced muscle wasting, and Opa1 and Drp1 double-knockout mice show muscle loss." (PMID 33264289, 2020). "Since we have recently established the contribution of unopposed mitochondrial fission to aging sarcopenia and lethality, we addressed whether balancing the loss of mitochondrial fusion by inhibiting fission-reverted Opa1 phenotype." (PMID 31208084, 2019). "The higher expression of Mfn2 and OPA1 observed in the soleus is particularly interesting because two recent studies showed that Mfn2 and OPA1 deficiencies are strongly involved in sarcopenia, aging-associated oxidative stress and unfolded protein response activation." (PMID 30449736, 2018). "Interestingly, genetic loss of function of Mfn2 and Opa1 in mice is sufficient to cause sarcopenia, suggesting that the down regulation we observed in sarcopenia could be causal in the loss of muscle mass and strength." (PMID 31862890, 2019). "MFN2 and OPA1 levels decreased from months 6 to 10, indicating reduced mitochondrial fusion during the progression of sarcopenia." (PMID 39971301, 2025). "The downregulation of Mfn2 and Opa1 expression in sarcopenia muscle suggests that mitochondrial fusion participate in the pathogenesis of sarcopenia." (PMID 37196123, 2023). "This mouse line — i.e., the inducible muscle-specific Opa1-KO — mimics the age-dependent decline of the fusion protein OPA1 in skeletal muscles of patients and mice with sarcopenia." (PMID 37551712, 2023). "Expression levels of Mfn2, Fis1, Drp1, and Opa1 in sarcopenic muscle are down-regulated, suggesting a role for mitochondrial dysfunction in the pathogenesis of sarcopenia and skeletal muscle atrophy." (PMID 36561214, 2022). "In line, MFN2, OPA1, or DRP1 deficiency negatively affect muscle health and mitochondrial homeostasis, triggering the insurgence of sarcopenia features, such as muscle atrophy." (PMID 35276842, 2022). "In another study, the expression levels of Mfn2, Fis1 and Opa1 were downregulated in sarcopenic muscle, suggesting that mitochondrial dynamics participates in the pathogenesis of sarcopenia." (PMID 34881083, 2021). "Thus, the findings in worm and Opa1–/– mice argue for a synergistic beneficial effect of RJx-01 in the treatment of sarcopenia." (PMID 37551712, 2023). "In addition, suppression of Mfn2 and OPA1 in skeletal muscles of elderly mice exacerbates metabolic changes and sarcopenia due to impaired mitochondrial quality and autophagy." (PMID 36561214, 2022). "In sarcopenia patients, Opa1 expression was reduced during senescence." (PMID 34881083, 2021). "To test the benefits of RJx-01 on muscle performance and molecular mechanisms relevant to sarcopenia, we employed multiple preclinical animal models, first Caenorhabditis elegans and subsequently 2 mouse models: an inducible muscle-specific optic atrophy 1–KO (OPA1-KO) mouse model and aged mice." (PMID 37551712, 2023).
sarcopenia (continued). "Deletion and inhibition of OPA1 also causes mitochondrial dysfunction, increased levels of IL6, IL1, ROS, mitochondrial DNA damage, and subsequent stimulation of transcription factors such as FoxO3 and NF-κB which are associated with sarcopenia and premature death." (PMID 36561214, 2022). "Similarly, mitochondrial fusion genes (Mfn2 and Opa1) were substantially downregulated in old SAMP8 mice and demonstrated a downward trend during the whole progression of sarcopenia." (PMID 34881083, 2021).
Blindness (13 papers, 2008 to 2024). Blindness is the condition of lacking visual perception defined as a profound reduction in visual perception. "In this cohort, the majority of patients presented with red/green color vision impairment or total color blindness, while only two patients carrying OPA1 mutations displayed yellow/blue color vision impairment, which is a typical color defect of ADOA." (PMID 34676220, 2021). "For example, mutations in OPA1, which encodes a conserved factor essential for mitochondrial fusion, lead to optic atrophy 1, a neurodegeneration that affects the optic nerve, eventually leading to blindness." (PMID 30658998, 2019). "Dysfunctional OPA1 mutations cause atrophy of the optic nerve leading to blindness." (PMID 30054480, 2018). "Having tested the hypothesis in several different ways and in different cohorts, we conclude that it is unlikely that genetic variation in OPA1 makes a major contribution to the risk of blindness in LHON mutation carriers." (PMID 21203403, 2010). "Recent linkage evidence raised the possibility that the nuclear gene optic atrophy 1 (OPA1) determines whether mtDNA mutation carriers develop blindness." (PMID 21203403, 2010). "While OPA1 is critical for optic nerve function, the mechanism by which OPA1 mutations lead to blindness is unknown." (PMID 18783614, 2008). "Mutation of OPA1 can lead to DOA and is one of the most common genetic causes of degeneration of retinal ganglion cells, leading to blindness." (PMID 19718456, 2009). "Our findings suggest that genetic variation in OPA1 is unlikely to make a major contribution to the risk of blindness in LHON mutation carriers." (PMID 21203403, 2010). "Our results indicate that, at least for OPA1, cardiac abnormalities are not completely manifest until the development of blindness." (PMID 23316298, 2012).
Hyperglycemia (13 papers, 2018 to 2025). An increased concentration of glucose in the blood. "Hyperglycemia induces OPA1 proteolytic cleavage, resulting in decreased mitochondrial matrix electron density and vacuolar degeneration." (PMID 40804395, 2025). "Hyperglycemia decreases Opa1 in neonatal rat cardiomyocytes, reducing mitochondrial potential and increasing apoptosis." (PMID 37895224, 2023). "In neonatal rat cardiomyocytes, hyperglycemia downregulates Opa1 and Mfn1 but upregulates Drp1 and Mfn2, affecting mitochondrial potential and increasing apoptosis." (PMID 37895224, 2023). "Hyperglycemia also induced O-GlcNAcylation of OPA1 in neonatal cardiac myocytes, thus reducing the mitochondrial length and suppressing complex IV activity." (PMID 36147470, 2022). "Increasing OPA1 protein level or decreasing OPA1 glycosylation could block hyperglycemia-related mitochondrial division." (PMID 36147470, 2022). "In addition, previous research has highlighted that hyperglycemia negatively regulates mitochondrial function in some cell types by altering mitochondrial fusion (regulated by OPA1) and fission (regulated by DRP1) dynamics leading increased mitochondrial fractionation." (PMID 36930661, 2023). "Similarly, it has been shown that hyperglycaemia increases the expression of fission proteins (e.g. dynamin‐related protein 1) and reduces the expression of fusion proteins (e.g. mitofusin 2 and Opa1)." (PMID 33453124, 2021). "Moreover, Opa1 deletion in pancreatic β cells impairs glucose-stimulated adenosine triphosphate (ATP) production and insulin secretion, which subsequently develops into hyperglycemia." (PMID 31551926, 2019). "Extracellular hyperglycemia and metabolic dysregulation create an energy stress in DCM, which reduce the interaction of OPA1 and FUNDC1, increasing mitochondrial fragmentation." (PMID 35450404, 2022). "We speculate that extracellular hyperglycemia and metabolic dysregulation in DCM might reduce the interaction of OPA1 and FUNDC1, thereby increasing mitochondrial fragmentation." (PMID 35450404, 2022). "Moreover, a study in ischemic brain has shown that hyperglycemia of T2DM produced a fragmented state, increasing Drp1 and decreasing Mfn2 and Opa1 levels, with alterations in the regulation of mitochondrial bioenergy." (PMID 32927647, 2020). "Therefore, we hypothesized that hyperglycemia affected mitochondrial dynamics by affecting the amplification of DRP1 and OPA1, thus affecting the progression of diabetic cognitive impairment, and further experiments are still needed for verification." (PMID 37563583, 2023). "Hyperglycemia resulted in a more pronounced decline of Opa1in WT than in normoglycemic group in all endpoints including non-ischemic control; however, it did not further decrease Opa1 in UCP2-/- mice." (PMID 33061796, 2020).
auditory neuropathy (12 papers, 2009 to 2025). A hearing disorder characterized by impaired transmission of signals through the auditory nerve, resulting in mild to severe hearing loss and poor speech perception. "MYO3 A, OTOF, and USH1 C are all associated with HC pathology, while OPA1 is associated with auditory neuropathy." (PMID 40268851, 2025). "Patients with autosomal dominant optic atrophy, induced by mitochondrial fusion gene OPA1 mutation, often experience hearing loss, which is similar to auditory neuropathy." (PMID 36278017, 2022). "Late-onset progressive auditory neuropathy has been reported in patients with OTOF or OPA1 mutations, this is consistent with our observation." (PMID 32555439, 2020). "We have previously characterized the hearing dysfunction affecting patients with DOA due to missense mutations in the OPA1 gene, who display impaired speech perception, severe abnormalities of ABRs and presence of OAEs consistent with auditory neuropathy." (PMID 31191217, 2019). "Indeed, OPA1 patients displayed the clinical profile of auditory neuropathy (AN) consisting of moderate hearing loss with disproportionate impairment of speech perception, abnormal brainstem responses and presence of normal otoacoustic emissions (OAE)." (PMID 31191217, 2019). "Genes underlying two common forms of auditory neuropathy are OTOF resulting in synaptopathy and OPA1 resulting in neuropathy of the spiral ganglion dendrites." (PMID 28174524, 2017). "Among non-isolated auditory neuropathy disorders, mutations in the OPA1 gene are believed to cause disruption of auditory nerve discharge by affecting the unmyelinated portions of human ANFs." (PMID 28174524, 2017). "Finally, neural factors, such as cochlear nerve hypoplasia or auditory neuropathy, as was observed in the subjects with pathogenic variants in CLRN1 and OPA1, respectively, may result in poorer outcomes." (PMID 40268851, 2025).
deafness (12 papers, 2009 to 2026). An inherited or acquired condition characterized by the complete loss of the ability to hear from one or both ears. "Targeted massively parallel sequencing of 158 deafness-related genes was performed, and individuals with OPA1 variants were identified." (PMID 41898875, 2026). "In the last decade, DOA clinical spectrum related to OPA1 variants has been extended to a wide variety of symptoms called DOAplus, combining deafness, ataxia, neuropathy, myopathy, Parkinsonism, and dementia." (PMID 38334784, 2024). "The association of DOA and deafness is frequently related to the c.1334G > A variant (p.R445H) in exon 14, but other OPA1 missense variants were reported in the literature." (PMID 38334784, 2024). "The combination of autosomal dominant optic neuropathy and deafness has been reported in families and in isolated cases with a heterozygous missense mutation in Optic atrophy-1 gene (OPA1; OMIM 605290)." (PMID 20069065, 2010). "Autosomal dominant optic neuropathy and deafness has also been reported in several families and in isolated cases with a heterozygous missense mutation (p.Arg445His or p.Gly439Val) in OPA1." (PMID 20069065, 2010). "On the basis of this study we advise to perform extensive genetic testing of at least WFS1 and OPA1 in cases of autosomal dominant optic neuropathy and deafness." (PMID 20069065, 2010).